ZBED6 (zinc finger BED-type containing 6)
Description:
Transcriptional repressor which binds to the consensus sequence 5'-GCTCGC-3', transcription regulation may be tissue-specific (By similarity). Regulates the expression of target genes such as: IGF2, PGAP6/TMEM8, ENHO, and PIANP (By similarity). Acts as a transcriptional repressor of growth factor IGF2, thereby negatively regulating postnatal growth of muscles and internal organs, especially in females (By similarity). Negatively regulates myoblast differentiation and myoblast mitochondrial activity via its regulation of IGF2 transcription (By similarity). Negatively regulates the cell cycle of myoblasts, potentially via transcriptional regulation of the E2F family of transcription factors such as: E2F1 and E2F2 (By similarity). Positively regulates the cell cycle and survival of pancreatic beta cells. Binds to the CDH2 gene and may directly repress CDH2 transcription (By similarity). Probably by controlling CDH2 expression, regulates pancreatic beta cell adhesion, and formation of cell-to-cell junctions between pancreatic beta cells and neural crest stem cells (By similarity). May also play a role in embryonic beta cell differentiation (By similarity). May play a role in insulin sensitivity and glucose clearance (By similarity).
Synonyms: MGR
Tractability: PROTAC: ubiquitination databases record sites on it.
Gene: Protein-coding gene on chromosome 1 (203,795,623 to 203,854,124, forward strand). Ensembl gene ENSG00000257315.
Subcellular location: Nucleus; Nucleus, nucleolus; Cytoplasm
Subcellular location (Human Protein Atlas): Nucleoplasm; Centriolar satellite
Gene Ontology:
Molecular function: DNA-binding transcription factor activity, RNA polymerase II-specific; DNA-binding transcription repressor activity, RNA polymerase II-specific; transcription cis-regulatory region binding; DNA binding; protein dimerization activity
Biological process: negative regulation of DNA-templated transcription; negative regulation of muscle cell differentiation; negative regulation of transcription by RNA polymerase II; regulation of transcription by RNA polymerase II; regulation of insulin secretion involved in cellular response to glucose stimulus
Cellular component: cytoplasm; nucleoplasm; nucleus; chromatin; nucleolus
Genetic constraint (gnomAD): Loss-of-function variants: 25 observed, 42.68 expected, observed/expected ratio (o/e) 0.59, 90% interval 0.43 to 0.82. The upper end of that interval is the gene's LOEUF score, 0.82, which puts it in group 3 of 6, group 1 being the genes least tolerant of losing a copy. Missense variants: 731 observed, 762.17 expected, observed/expected ratio (o/e) 0.96, 90% interval 0.9 to 1.02. Synonymous variants: 281 observed, 266.55 expected, observed/expected ratio (o/e) 1.05, 90% interval 0.96 to 1.16.
Homologues: Orthologues: dog ZBED6 (93% identical), pig ZBED6 (91% identical), guinea pig ZBED6 (91% identical), rat Zbed6 (89% identical), mouse Zbed6 (89% identical), rabbit ZBED6 (88% identical), Caenorhabditis elegans K09A11.1 (12% identical), Caenorhabditis elegans C10A4.1 (10% identical), Drosophila melanogaster CG13775 (9% identical), Caenorhabditis elegans B0545.4 (2% identical). Paralogues in human: ZBED4 (23% identical), ZBED1 (14% identical).
Diseases named in the same sentence as ZBED6 in open-access papers:
ZBED6 is named in the same sentence as 23 diseases in open-access papers, as found by Europe PMC text mining. Sharing a sentence is not in itself a finding about the gene and the disease. The quoted sentences say what the papers report.
colorectal cancer (5 papers, 2015 to 2023). A primary or metastatic malignant neoplasm that affects the colon or rectum. "Moreover, other zinc finger BED-type transcription factors, such as ZBED3 and ZBED6, are implicated in cancer progression in lung cancer cells and colorectal cancer cells, respectively." (PMID 35052473, 2022).
Atrophy (2 papers, 2023 to 2025). Any weakening or degeneration, especially through lack of use. "By employing porcine and murine models of muscle atrophy, the present study was aimed at elucidating the critical role of ZBED6 in preserving myofibre size during age‐ and glucocorticoid‐induced muscle atrophy." (PMID 40464206, 2025). "Notably, our findings demonstrated that the depletion of ZBED6 attenuated muscle atrophy by downregulating the expression of Dkk3, a key regulator of muscular atrophy, by directly binding to its promoter region." (PMID 40464206, 2025).
diabetes (2 papers, 2023 to 2025). "The inhibitory effects of ZBED6‐KO on obesity and muscle atrophy may also mitigate the muscle atrophy induced by existing drugs used for the treatment of obesity, providing potential insights for the development of novel therapeutic targets for obesity and diabetes." (PMID 40464206, 2025).
Sepsis (2 papers, 2023 to 2025). Sepsis is defined as life-threatening organ dysfunction caused by a dysregulated host response to infection. "We validated this conclusion in ZBED6‐deficient pigs and human patients diagnosed with sepsis‐induced muscle atrophy." (PMID 37551034, 2023). "Together, these results suggest a potential association between sepsis‐induced muscle loss and increased ZBED6 expression in septic pigs." (PMID 37551034, 2023). "Together, these results demonstrate that DOCK3 is essential for the protective role of ZBED6 deficiency on sepsis‐induced muscle atrophy." (PMID 37551034, 2023). "Furthermore, ZBED6‐KO has been shown to mitigate the loss of Type II myofibres induced by sepsis in pigs." (PMID 40464206, 2025). "Additionally, ZBED6‐KO is associated with elevated muscle growth rates and higher muscle mass in pigs and mice and has been shown to protect against sepsis‐induced muscular atrophy in pigs by targeting DOCK3." (PMID 40464206, 2025). "Furthermore, our previous study showed a broad tissue distribution of ZBED6, and deficiency of ZBED6 affects multiple internal organs including heart and liver.[14a] This opens a range of relevant questions in sepsis where multiple organs are affected." (PMID 37551034, 2023). "Protection against sepsis‐induced muscle wasting in ZBED6‐deficient pigs is further demonstrated." (PMID 37551034, 2023). "Markedly higher levels of urea and urea‐to‐creatinine ratio were shown in septic WT pigs than in their sham controls, whereas these parameters were not elevated in septic ZBED6−/− pigs, suggesting a protection of ZBED6 deficiency against sepsis‐induced muscle catabolism." (PMID 37551034, 2023). "The loss of ZBED6 upregulates the expression of DOCK3, leading to the hyperactivation of its downstream RAC1/PI3K/AKT signalling cascade, which in turn attenuates sepsis‐induced muscle atrophy." (PMID 40464206, 2025). "We show a positive correlation between ZBED6 expression and muscle atrophy, as well as depletion of ZBED6 protects against sepsis‐induced muscle atrophy." (PMID 37551034, 2023). "Our findings suggest that ZBED6 is a promising therapeutic target for sepsis‐induced muscle atrophy, with potential clinical applications for the treatment of muscle loss in sepsis." (PMID 37551034, 2023). "In septic ZBED6‐deficient pigs, DOCK3 expression is increased in skeletal muscle and myocytes, activating the RAC1/PI3K/AKT pathway and protecting against sepsis‐induced muscle wasting." (PMID 37551034, 2023). "In this study, we identified ZBED6 as a potential target for sepsis‐induced muscle atrophy by creating a modified septic pig model with CLP procedure." (PMID 37551034, 2023). "Targeting zinc finger BED‐type containing 6 (ZBED6) for sepsis‐induced muscle atrophy evidence from humans and pigs." (PMID 37551034, 2023). "Together, these results indicate that ZBED6 ablation rescues sepsis‐induced muscle atrophy by maintaining the dynamic equilibrium between protein degradation and synthesis." (PMID 37551034, 2023). "In contrast, skeletal muscles from sepsis patients with muscle atrophy showed significantly increased protein levels of ZBED6 and reduced levels of DOCK3/RAC1‐GTP/p‐AKT." (PMID 37551034, 2023). "DOCK3 overexpression was sufficient to rescue aggravated sepsis‐induced atrophy in ZBED6‐overexpressing myotubes." (PMID 37551034, 2023). "Together, these results suggest that depletion of ZBED6 protects against sepsis‐induced muscle atrophy." (PMID 37551034, 2023). "In contrast, ZBED6 overexpression in myotubes exacerbated sepsis‐induced muscle atrophy, exhibiting small myotube diameter and high expression levels of ATROGIN‐1, accompanied with reduced levels of DOCK3." (PMID 37551034, 2023). "ZBED6 deficiency increased DOCK3 expression, leading to hyperactivation of its downstream RAC1/PI3K/AKT signaling cascade, thus preventing sepsis‐induced muscle atrophy." (PMID 37551034, 2023).
Sepsis (continued). "Zinc finger BED‐type containing 6 (ZBED6), a transcriptional repressor, enhances muscle growth and protects against sepsis‐induced atrophy, but its role in ageing‐ and dexamethasone (Dex)‐induced muscle atrophy remains unknown." (PMID 40464206, 2025). "One limitation of our investigation is the absence of evidence regarding the effects of ZBED6 deficiency, apart from ameliorating sepsis‐triggered muscle atrophy, on the dysfunction of other organs that are often affected during sepsis." (PMID 37551034, 2023). "Whether ZBED6 also contributes to the multiorgan injuries induced by sepsis is another fertile area for future research." (PMID 37551034, 2023). "A similar average daily food intake was observed in two groups of pigs, suggesting that prevention of sepsis‐induced muscle atrophy in ZBED6‐deficient pigs was not attributed to increased energy intake." (PMID 37551034, 2023). "Further research is necessary to explore the systemic role of ZBED6 in sepsis." (PMID 37551034, 2023). "High mRNA and protein levels of ZBED6 were shown in muscle tissues of the sepsis patients." (PMID 37551034, 2023). "Our study extended a protective role of DOCK3 in sepsis‐induced muscle atrophy and elucidated its upstream transcription factor ZBED6 and downstream RAC1/PI3K/AKT pathway, revealing a novel regulatory mechanism of DOCK3 underlying the occurrence of muscle atrophy." (PMID 37551034, 2023). "Notably, sepsis patients show increased ZBED6 expression along with reduced DOCK3 and downregulated RAC1/PI3K/AKT pathway." (PMID 37551034, 2023). "Together, these results suggest that the upregulation of ZBED6 may be a crucial factor contributing to sepsis‐induced muscle atrophy." (PMID 37551034, 2023). "Nonetheless, ZBED6 deficiency greatly attenuated sepsis‐induced reduction in myofiber CSA, without obviously affecting the relative frequency distribution." (PMID 37551034, 2023). "With this model and sepsis patients, increased levels of the transcription factor zinc finger BED‐type containing 6 (ZBED6) in skeletal muscle are shown." (PMID 37551034, 2023). "Thus, to explore whether ZBED6 plays a key role in the regulation of sepsis‐induced muscle atrophy with a suitable model, we developed a modified CLP pig model to mimic the whole course of sepsis in the presence or absence of ZBED6 (ZBED6‐deficient pigs and WT controls)." (PMID 37551034, 2023). "Knockdown of DOCK3 in myotubes abolished the resistance to sepsis‐induced myotube atrophy by ZBED6 shRNAs, showing reduced myotube diameter and elevated ARTOGIN‐1, suggesting that ZBED6 knockdown protects myotubes from sepsis‐induced atrophy by upregulating DOCK3." (PMID 37551034, 2023).
glioblastoma (1 paper, 2024). The most malignant astrocytic tumor (WHO grade IV). "We mainly verified the regulatory effects of KHDRBS1, SNORD51 and ZBED6 on pentose phosphate pathway and malignant biological behavior in glioblastoma cells, such as proliferation, migration and invasion." (PMID 39516455, 2024).
glioma (1 paper, 2024). A benign or malignant brain and spinal cord tumor that arises from glial cells (astrocytes, oligodendrocytes, ependymal cells). "According to enrichment scores, top 10 genes of ROS pathway were selected, which were related to ZBED6 in glioma samples." (PMID 39516455, 2024).
Glucose intolerance (1 paper, 2021). Glucose intolerance (GI) can be defined as dysglycemia that comprises both prediabetes and diabetes. "However, in Zbed6-KO (Nnt+/Nnt+) mice fed an HFD, glucose intolerance developed, suggesting that the combination of a reduced beta cell mass and a diet overload is necessary to cause impaired beta cell function." (PMID 34296320, 2021). "Zbed6 knockout mice, but not wild-type mice, developed glucose intolerance when given a high-fat diet." (PMID 34296320, 2021). "The lowered beta cell mass of Zbed6-KO mice did not promote glucose intolerance when given an CD, but as the mice were of the Nnt+/Nnt+ genotype, a milder beta cell phenotype can be expected." (PMID 34296320, 2021). "ZBED6 may act, at least in part, by restricting PRC-mediated mitochondrial activation/ROS production, which may lead to protection against beta cell dysfunction and glucose intolerance in vivo." (PMID 34296320, 2021).
Impaired glucose tolerance (1 paper, 2021). An abnormal resistance to glucose, i.e., a reduction in the ability to maintain glucose levels in the blood stream within normal limits following oral or intravenous administration of glucose. "A clue to why Zbed6-KO promotes impaired glucose tolerance in HFD-treated mice may be that the expression of islet oxidative phosphorylation genes was increased in vivo." (PMID 34296320, 2021).
muscular atrophy (1 paper, 2025). The loss of muscle tissue due to inactivity or disease. "The findings additionally demonstrated that Dex, a glucocorticoid analogue, induced myotube atrophy and significantly upregulated the expression of Zbed6 in C2C12 cells, suggesting a novel role for Zbed6 in Dex‐induced muscular atrophy." (PMID 40464206, 2025).
Myocardial fibrosis (1 paper, 2026). "In summary, the protective effect of ZBED6 against myocardial fibrosis injury is achieved through the inhibition of Piezo1 transcription, leading to reduced YAP nuclear translocation." (PMID 41555028, 2026).
myocardial infarction (1 paper, 2026). Gross necrosis of the myocardium, as a result of interruption of the blood supply to the area, as in coronary thrombosis. "Cardiac injury was evaluated by echocardiography and Masson staining in myocardial infarction (MI) mice with zinc finger BED-type containing 6 (ZBED6) knockdown or overexpression." (PMID 41555028, 2026).
Obesity (1 paper, 2025). Accumulation of substantial excess body fat. "Previous studies have demonstrated that Zbed6‐KO also protects against obesity and insulin sensitivity induced by high‐fat diets, suggesting that it may also attenuate obesity‐ or T2D‐induced muscle atrophy." (PMID 40464206, 2025). "However, further research is necessary for understanding the contributions of ZBED6 in obesity‐induced muscle atrophy." (PMID 40464206, 2025).
overnutrition (1 paper, 2021). An imbalanced nutritional status resulting from excessive intake of nutrients. "Thus, it seems that overnutrition predisposes for augmented beta cell ROS production, and in the case when ZBED6 does not restrict mitochondrial activation by dampening PRC gene expression, potentially harmful levels of ROS may be generated." (PMID 34296320, 2021).
type 1 diabetes (1 paper, 2021). "The most important beta cell autoantigens in type 1 diabetes (Ins1/2, Slc30a8, Ica1, Gad1, Ptprn2) were expressed at higher levels in Zbed6-KO islets." (PMID 34296320, 2021).
type 2 diabetes (1 paper, 2021). "The role of ZBED6 in the pathophysiology of type 2 diabetes remains to be clarified, but it is tempting to speculate that ZBED6 maintains beta cell survival and proliferation at the cost of decreased insulin production, and that this is beneficial during long-term high-fat overfeeding." (PMID 34296320, 2021).
tumor (7 papers, 2009 to 2026). "In this study, nude mice were divided into five groups to be respectively injected different GBM cells for verifying the roles of KHDRBS1, SNORD51 and ZBED6 in tumor growth." (PMID 39516455, 2024). "Finally, our in vivo study showed that the combination of KHDRBS1 knockdown, SNORD51 knockdown and ZBED6 overexpression significantly reduced the volume of the xenograft GBM tumor and prolonged the survival time of nude mice." (PMID 39516455, 2024). "Spatial analysis confirms the co-localization of ZBED6 and PIK3C3 in tumor tissues." (PMID 41858898, 2026). "ZBED6 is not affected in the CRISPR KO cell line, and the delayed tumor growth of HeLa-KO-ZC3 is a strong indication that specific targeting of ZC3H11A can result in a therapeutic effect." (PMID 39582529, 2024).
ZBED6 also shares sentences with these, for which no sentence is quoted: cancer (4 papers); age (1); Alzheimer disease (1); Cachexia (1); colitis (1); leukocytosis (1); lung carcinoma (1).